RNU6-915P (RNA, U6 small nuclear 915, pseudogene)
Gene: Small nuclear RNA gene on chromosome 2 (195,670,372 to 195,670,474, reverse strand). Ensembl gene ENSG00000201813.
Homologues: Orthologues: chimpanzee U6 (97% identical), macaque U6 (91% identical), mouse Gm23167 (69% identical), rat LOC120100199 (66% identical). Paralogues in human: RNU6-1038P (85% identical), RNU6-1158P (83% identical), RNU6-140P (83% identical), RNU6-38P (83% identical), RNU6-476P (83% identical), RNU6-1029P (83% identical), RNU6-1124P (83% identical), RNU6-116P (83% identical), RNU6-1237P (83% identical), RNU6-144P (83% identical), RNU6-25P (83% identical), RNU6-284P (83% identical), and 1287 more.